TRIM26 (tripartite motif containing 26)
Diseases named in the same sentence as TRIM26 in open-access papers (continued):
Sharing a sentence is not in itself a finding about the gene and the disease.
infection (continued). "Our earlier work to examine interactions between HSV-2 and vaginal epithelial cells demonstrated that infection of the human vaginal epithelial cell line (VK2) with HSV-2 resulted in increased expression of TRIM26, a negative regulator of the Type I interferon pathway." (PMID 33419081, 2021). "It was found that protein levels of TRIM26 increased significantly at 12 and 24 h post infection." (PMID 33419081, 2021). "While, a considerable proportion of TRIM26 moved into nucleus after infection with SeV and VSV." (PMID 25763818, 2015). "Additionally, it is important to explore whether the physiological roles of TRIM26 observed in vitro are consistently replicated in animal models during the natural course of infection." (PMID 39596676, 2024). "The murine ortholog of tripartite motif 26 (TRIM26), an E3 ubiquitin ligase necessary for the formation of the HCV replication organelle (RO) in human infections, is unable to interact with HCV NS5B, accordingly abrogating ubiquitination and RO establishment." (PMID 40899815, 2025). "We separately humanized the murine TRIM26 locus, a factor that had previously been demonstrated to be necessary for forming HCV ROs during infection." (PMID 40899815, 2025). "Next, we established HeLa stable cells expressing TRIM8, TRIM25, TRIM26, TRIM32, and TRIM33 to evaluate their effects on VEEV-TC83-GFP infection." (PMID 39527628, 2024). "At 4 days post-infection, both the transcriptional level of CXCL1 in the kidney and the secretion of CXCL1 in the serum were higher in Trim26–/–mice." (PMID 38166150, 2024). "We found Trim26–/–mice had higher levels of proinflammatory cytokine expression than Trim26+/+ mice, including IL-6, IL-1β, and TNF-α at day 5 post-infection." (PMID 38166150, 2024). "After stimulation with LPS and poly(I:C) or infection with SeV and VSV, macrophages from TRIM26-Tg mice showed less IFN-β expression and secretion, compared to the macrophages from WT mice." (PMID 25763818, 2015). "To assess the effect of Trim26 on specific myeloid cell infiltration in the mouse C. albicans infection model, we harvested leukocytes from the kidneys and determined their immunophenotypes using FACS on days 1, 2, 3, 4, 5, and 7 post-infection." (PMID 38166150, 2024). "Infection of WT cells leads to IRF3 activation and pIRF3 location in the nucleus as expected, but this does not occur in TRIM26 OE cells and is exaggerated in the response of TRIM26 KO cells." (PMID 33419081, 2021). "It would be interesting to further investigate whether and which HSV proteins interact with TRIM26 and other TRIM proteins and determine if those interactions alter infection and intrinsic immunity." (PMID 33419081, 2021). "However, the secretion of CXCL1 showed no significant different at early time points after infection (12 and 24 h) in Trim26–/–mice." (PMID 38166150, 2024). "However, TRIM26 OE cells showed no increase of IFN-β after infection compared to WT VK2 cells." (PMID 33419081, 2021). "Notably, IRF3 5A was not degraded by TRIM26 even under the condition of infection with SeV and VSV." (PMID 25763818, 2015). "This indicates that over-expression of TRIM26 leads to substantial reduction in IFR3, while in normal cells modest baseline IRF3 activity is seen in the absence of infection." (PMID 33419081, 2021). "Interestingly, analysis of ISG expression indicates that TRIM26 OE cells had no significant increase in MX1 and ISG15 expression after infection, in contrast to WT VK2 and TRIM26 KO cells, suggesting that TRIM26 may have a direct regulatory role for these ISGs." (PMID 33419081, 2021).
liver (2 papers, 2020 to 2023). "The hepatocyte-specific Trim26 deletion interrupts hepatic metabolism homoeostasis, is accompanied by elevated lipid deposition, the glucose metabolic syndrome, and liver inflammation, and dramatically accelerates the development and progression of NASH." (PMID 37821436, 2023).
hematological malignancies (1 paper, 2024). "Although the function of the ubiquitinated TRIM26 protein has not yet been studied in the context of hematological malignancies, the importance of the USP39/ZEB1/TRIM26 axis deserves to be investigated in the context of MM." (PMID 39736693, 2024).
neurological diseases (1 paper, 2024). "At the same time, we have illustrated the role of TRIM26 in disease development, including tumors and neurological disorders." (PMID 38956921, 2024).
TRIM26 also shares sentences with these, for which no sentence is quoted: breast carcinoma (4 papers); depression (2); multiple sclerosis (2); acute promyelocytic leukemia (1); anxiety disorder (1); autism (1); autistic spectrum disorders (1); bipolar disorder (1); cholangiocarcinoma (1); colorectal tumors (1); COVID-19 (1); eczema (1); endometrial adenocarcinoma (1); endometrial cancer (1); esophageal carcinoma (1); gastric adenocarcinoma (1); gastric cancer (1); head and neck squamous cell carcinoma (1); HIV-1 infection (1); Hypertension (1); liver cirrhosis (1); lung adenocarcinoma (1); melanoma (1); Obesity (1); pancreatic cancer (1); prostate (1); rectal adenocarcinoma (1); renal cell carcinoma (1); rheumatoid arthritis (1); thyroid carcinoma (1).
A further 2 diseases each share a sentence with TRIM26 in 1 paper.